FOXO1 (forkhead box O1)
Diseases named in the same sentence as FOXO1 in open-access papers (continued):
Sharing a sentence is not in itself a finding about the gene and the disease.
Hyperglycemia (continued). "Oxidative stress or hyperglycemia induce FOXO1 deacetylation in vascular endothelial cells, that contributes to the increased risk of atherosclerosis in diabetic patients." (PMID 25273948, 2014). "In this case, the phosphorylation of the AKT can be attenuated so that the inactivated AKT cannot perform the function to FOXO1 and lead to hyperglycemia." (PMID 25530976, 2014). "Most importantly, in the present study we demonstrated acetylation of FoxO1 in the liver is involved in OA-induced memory for the control of hyperglycemia." (PMID 25222566, 2014). "Oral intubation of SA ameliorates hyperglycemia in db/db mice by reducing hepatic gluconeogenesis through the decrease of Sirt1 expression and increase in acetylated FoxO1." (PMID 25610880, 2014). "In accordance with these results, we observed that aging associated with weight gain and adiposity reduced Akt activity and Foxo1 phosphorylation, contributing to fasting hyperglycemia." (PMID 23442260, 2013). "Therefore, FoxO1 overexpression in pancreatic duct cells increases duct cell proliferation, which leads to pancreatic cyst formation, but at the same time it also inhibits β cell neogenesis from duct progenitors, resulting in the loss of β cells and hyperglycemia." (PMID 22384192, 2012). "In this study we investigated TG mice expressing active FoxO1 specifically in pancreas and showed that TG mice exhibit hyperglycemia." (PMID 22384192, 2012). "The over-expression of FOXO1 suppresses oxidative stress under hyperglycemia or abnormal glucose metabolism." (PMID 21318024, 2011). "Notably, the experimental suppression of FMO3 in insulin-resistant mice effectively inhibited FoxO1, a key metabolic regulatory node, and completely circumvented the progression of hyperglycemia, hyperlipidemia, and atherosclerosis." (PMID 40395816, 2025). "Additionally, FoxO1 genetic inactivation exacerbated lipid metabolism abnormalities during hyperglycemia." (PMID 39533662, 2025). "Thus, PRMT1, specifically the PRMT1V2 isoform, promotes the pathogenesis of NAFLD by methylating key transcriptional regulators such as PGC‐1α and FOXO1, thereby augmenting hepatic gluconeogenesis and exacerbating hyperglycemia." (PMID 41256732, 2025). "However, persistent hyperglycemia can lead to reduced FoxO1 expression, compromising β-cell identity and function, thereby contributing to β-cell dedifferentiation." (PMID 40749831, 2025). "Decreased phosphorylation of FOXO1 affects its protein levels and transcriptional activity, activating genes related to gluconeogenesis, thereby increasing glucose production and exacerbating hyperglycemia in insulin-resistant cells." (PMID 40951426, 2025). "Furthermore, we investigated the potential mechanisms by which QCT and SS abate hyperglycemia-induced dysregulation of hepatic gluconeogenesis and associated complications and orchestrate the PI3K/Akt/FOXO1 signaling pathway." (PMID 39846548, 2025). "Thus, hyperglycemia can be improved by reducing gluconeogenesis through AKT/FOXO1-mediated PEPCK and G6Pase regulation and by increasing glycogen synthesis." (PMID 37432173, 2023). "Among these miRNAs, miR-542-5p and miR-182 could lead to potential hyperglycemia and modulate the insulin secretion by targeting FOXO1." (PMID 37373469, 2023). "The inhibition of FoxO1 reduces hyperglycemia-evoked apoptosis of ECs." (PMID 37172821, 2023). "Furthermore, we found that up-regulation of FoxO1 or FoxO3a is attributable to the reduction of H9c2 cardiac cells apoptosis and autophagy induced by hypoxia/reoxygenation injury under hyperglycemia in vitro." (PMID 36035917, 2022). "The overexpression of SIRT3 suppresses hyperglycemia-induced senescence of human diploid fibroblasts by deacetylating FOXO1 and increasing catalase and manganese superoxide dismutase (MnSOD) in WI-38 cell and is implicated as a potential target to treat diseases of senescence." (PMID 34847835, 2022).
Hyperglycemia (continued). "In mice lacking FoxO1 in β cells, FoxO1 ablation caused hyperglycemia with reduced β cell mass, following physiologic stress such as multiparity and aging." (PMID 36232796, 2022). "Similarly, the liver-specific ablation of FoxO1 was shown to mitigate stress-induced hyperglycemia and hyperinsulinemia, indicating an improvement of systemic insulin sensitivity upon FoxO1 inactivation." (PMID 36232456, 2022). "In a previous study, we revealed that propofol postconditioning could attenuate hypoxia/reoxygenation-induced apoptosis and autophagy by regulating the expression of FoxO1 and FoxO3a in H9c2 cell under hyperglycemia." (PMID 36035917, 2022). "Interestingly, we also found that up-regulation of FoxO1 or FoxO3a decreased the ROS level in H9c2 cells, a cardiac cell strain derived from the S-D Rat left ventricle, under the condition of hyperglycemia." (PMID 36035917, 2022). "Moreover, FOXO-1 binding was detected at a FOXO-1 consensus DNA binding sequence identified in the PlGF promoter, and enriched ~ fourfold following exposure of the cells to hyperglycaemia." (PMID 34381074, 2021). "After having identified the optical concentration of propofol, H9c2 cells were subjected to H/R and P-PostC in the absence or presence of FoxO1 or FoxO3a gene silencing to explore their roles in P-PostC mediated protection against apoptotic and autophagic cell deaths under hyperglycemia." (PMID 34753510, 2021). "In the current study, we speculated that P-PostC may attenuate hypoxia/ reoxygenation-induced apoptosis and autophagy by regulating the expression of FoxO1 and FoxO3a in H9c2 cell under hyperglycemia." (PMID 34753510, 2021). "In the β-cell-specific FoxO1 knockout mice, a decrease in pancreatic β-cells and an increase in α-cells was observed under metabolic stress conditions such as aging or high fertility, resulting in hyperglycemia." (PMID 33918379, 2021). "Finally, SIRT1 and SIRT3 are involved in oxidative stress management: SIRT1 protects, through activation of FOXO1, cells against hyperglycemia-induced oxidative stress, whereas SIRT3 protects pancreatic cells in mice against palmitate-induced stress." (PMID 33806509, 2021). "In this study, we demonstrate that hyperglycaemia directly up-regulates PlGF by suppression of PI3K/Akt signalling resulting in an increase in FOXO1 activity and binding to the PlGF promoter in endothelial cells, and increased FOXO1 activity promotes PlGF expression in vivo." (PMID 34381074, 2021). "Based on the findings, propofol post-treatment promotes cell survival through inhibiting apoptosis and autophagy induced by hypoxia/reoxygenation in H9c2 cells under hyperglycemia, and that activation of FoxO1 and FoxO3a expression is key for propofol to confer such cardiac protection." (PMID 34753510, 2021). "Thereafter, FoxO1 is proteolyzed and eliminated when hyperglycemia persists." (PMID 33918379, 2021). "Furthermore, it was reported that the protective effect of RSV is achieved by inhibiting the expression of FoxO1 to promote angiogenesis in hyperglycemia." (PMID 34946610, 2021). "Moreover, Akt inhibition triggers the activation of the transcription factor forkhead box protein O1 (Foxo1), which increases the expression of key enzymes of gluconeogenesis, leading to hyperglycemia." (PMID 32455840, 2020). "Hyperglycaemia‐induced FoxO1 plays an important role in inducing pro‐inflammatory cytokines." (PMID 33108705, 2020). "Furthermore, FOXO1 is already active in young Cdk1 cKO mice, exacerbating hyperglycemia via gluconeogenesis." (PMID 33345777, 2020). "In the present study, FoxO1 was consistently found to be highly expressed in carotid arteries, accompanied by hyperglycaemia‐induced vascular remodelling, while FoxO1 inhibitor ameliorated the hyperglycaemia‐induced SMCs decrease in carotid medium of type 1 diabetic rats." (PMID 33108705, 2020).
Hyperglycemia (continued). "In the present study, we investigated hepatic steatosis in relation to hyperglycemia in the context of aging, as well as FoxO1 interaction with PPARγ during ER stress, in both the liver and AC2F cells, to achieve a better understanding of the molecular mechanisms involved in hepatic lipogenesis." (PMID 31246177, 2019). "We further investigated whether Foxo1 overexpression could attenuate the protein indicators of apoptosis and interstitial fibrosis induced by hyperglycemia in mouse RPTCs." (PMID 30962862, 2019). "Hyperglycemia may further increase the macrophage inflammatory phenotype by reducing the capacity of FoxO1 to stimulate IL-10 expression." (PMID 31849924, 2019). "We hypothesized that repression of transcriptional activity of forkhead box O1 (FoxO1) via histone deacetylase inhibitors (HDACi) ameliorates hyperglycemia in type 2 diabetic rats." (PMID 30424007, 2018). "Also, from hyperglycemia models and high glucose treatment, it is able to activate FoxO1 via phosphorylation and O-GlcNAcylation, instead of direct regulation in FoxO1 expression." (PMID 30002415, 2018). "Additionally, due to reduction of SIRT activity and its expression in DM, FOXO1 is acetylated and activated which leads to hyperglycemia." (PMID 31565649, 2018). "Here, we hypothesize that repression of transcriptional activity of forkhead box O1 (FoxO1) via histone deacetylase inhibitors (HDACi) ameliorates hyperglycemia in T2DM rats." (PMID 30424007, 2018). "Thus, in ob/ob mice, as in LIRKO mice, the knockdown of FMO3 can activate SREBP-2/miR-182 and suppress FoxO1 and hyperglycaemia." (PMID 25849138, 2015). "Among the molecular mechanisms involved, we emphasize in this review the participation of TRB3 protein (a mammalian homolog of Drosophila tribbles), which is able to inhibit Akt activity and, thereby, maintain Foxo1 activity in the nucleus of hepatocytes, inducing hyperglycemia." (PMID 26288661, 2015). "FOXO1 is deacetylated in response to oxidative stress and hyperglycemia." (PMID 25273948, 2014). "Data from this study demonstrated that hyperglycemia accelerates aging-like process in the vascular ECs and such process is mediated via downregulation of SIRT1, causing reduction of mitochondrial antioxidant enzyme in a p300 and FOXO1 mediated pathway." (PMID 23342163, 2013). "Indeed, chronic hyperglycemia can lead to hyperglycosylation of FOXO1, thus inducing G6pc, Pck1 and Ppargc1a genes, and causing further production of hepatic glucose." (PMID 22110478, 2012). "To gain mechanistic insights into whether OC could restore pancreatic gene expression of insulin and PDX1 under conditions of hyperglycemia, we further examined the gene expression of FOXO1, PDX1 and insulin in β-cells cultured with OC, with or without the AKT inhibitor." (PMID 40585255, 2025). "Consequently, this aberrant FoxO1 activation promotes the transcription of key gluconeogenic enzymes, such as phosphoenolpyruvate carboxykinase and glucose‐6‐phosphatase, exacerbating fasting hyperglycemia and insulin resistance in NAFLD." (PMID 41256732, 2025). "Indeed, either haploinsufficiency or liver-specific inactivation of FoxO1 have been shown to inhibit gluconeogenesis and reduce fasting hyperglycemia in insulin-resistant mice by decreasing hepatic expression of gluconeogenic genes and improving peripheral glucose tolerance." (PMID 36232456, 2022). "Furthermore, manipulation of gut microbiota or knockdown of FMO3 in insulin-resistant mice inhibited TMAO production, reduced PERK activation and suppressed FoxO1 in the liver, which may prevent the development of hyperglycemia." (PMID 35982495, 2022). "Interestingly, abnormal elevation of hepatic glucose production is known to contribute to fasting hyperglycemia in T2D, and in a diabetic murine model increased gluconeogenesis promoted by FOXO1 seems to be ascribable to decreased FOXP1 expression in the liver." (PMID 33664777, 2021).
Hyperglycemia (continued). "This might decrease weight and increase hyperglycemia through activation of FOXO1 and GLUT4." (PMID 32599690, 2020). "Sustained hyperinsulinemia and hyperglycemia with compromised insulin/IRS2/FOXO1 signaling yields high expression of MTP and apoC-III with an overproduction of TG-VLDL1 yet causes of compromised insulin/IRS2/FOXO1 signaling remain unclear." (PMID 28550272, 2018). "One possible explanation for this phenotype was that because hyperglycemia-induced oxidative stress leads to FoxO1 activation by acetylation-dependent mechanism as we previously reported, the effect of FoxO1 on lipid metabolism might only become apparent in hyperglycemic conditions." (PMID 23056614, 2012). "Downregulation of miR-27a/b increases FOXO1 expression, enhancing PEPCK and G6pase, leading to hepatic gluconeogenesis and hyperglycemia." (PMID 41009556, 2025). "In liver, ROS inhibit AKT phosphorylation, enabling nuclear FoxO1 to upregulate gluconeogenic (PEPCK, G6Pase) and lipogenic genes, exacerbating hyperglycemia and steatosis." (PMID 41037185, 2025). "Genistein is capable of modulating hyperglycemia by activating the hepatic IRβ/PI3/AKT signaling pathway, increasing the phosphorylation of hepatic Foxo1/GSK3β and improving glucose metabolism of liver." (PMID 36570152, 2022). "SIL promotes the expression of SIRT1, FoxO1, CAT, GPX1 and SOD2 of hyperglycemia Intervention of MC3T3-E1 by reducing intracellular ROS levels and restoring the activity and function of MC3T3-E1, similar to those from some researches." (PMID 36057883, 2022). "Many studies have shown that activating FXR can improve hyperglycemia and hyperlipidemia by both suppressing hepatic gluconeogenesis via FXR/miR-22-3p/PI3K/AKT/FoxO1 pathway and promoting glycogen synthesis through FXR/miR-22-3p/PI3K/AKT/GSK3β pathway." (PMID 36465656, 2022). "This is consistent with our findings of reduced Akt phosphorylation in HUVEC incubated under hyperglycaemia, both under basal conditions and in the presence of IGF-1, and corresponding changes in FOXO1 phosphorylation/activity in these cells." (PMID 34381074, 2021). "In conclusion, SET8 interacted with FOXO1 to modulate PTEN expression in vascular endothelial cells, thus contributing to hyperglycemia-mediated endothelial inflammation." (PMID 33028948, 2020). "On the other side, oxidative stress-induced hyperglycemia and cytokine toxicity was repressed by SIRT1 via deacetylating forkhead box O1 (FOXO1) and the NF-κB subunit p65 on β-cells, respectively." (PMID 30559718, 2018). "Integrating miR-182 tissue expression profile, target genes, and copy number in blood reveals that miR-182 plays a key role in crucial genes modulation, such as FOXO1 and BHLHE22, which leads to potential hyperglycemia and modulates the insulin secretion." (PMID 25530976, 2014). "Hence, in the present study, we aimed to analyze the possible role of antioxidant vitamins (C and E) in reducing the glyphosate-mediated development of hyperglycemia and hyperinsulinemia by downregulating the expression of GSK-3β and FOXO-1 mRNA in the liver." (PMID 38274944, 2023). "The findings of the present in vivostudy clearly demonstrate that antioxidant vitamins (C and E), reduce hyperglycemia and hyperinsulinemia by upregulating GSK 3β and FOXO1 proteins involved in glucose metabolism and insulin signaling caused by glyphosate exposure." (PMID 38274944, 2023). "In conclusion, HMC could ameliorate hyperglycemia through PI3K/AKT pathway in skeletal muscles and improve the FOXO1 pathway in the livers of ob/ob mice." (PMID 37432173, 2023). "In the process of T2D, hyperglycemia and hyperlipidemia could activation JNK phosphorylation to augment Forkhead box protein O1 (FOXO1), which is a transcription factor to regulate insulin synthesis in β-cells." (PMID 26147439, 2015).
Hyperglycemia (continued). "Although FOXO1 may be a crucial target in the treatment of metabolic illnesses, such as T2DM, hyperglycemia, etc., there is little evidence to support the effect of quercetin on FOXO1." (PMID 38674793, 2024). "However, it is unknown whether glyphosate can induce hyperglycemia by interfering with GSK-3β and FOXO-1, proteins involved in the regulation of glucose metabolism and insulin signaling in hepatocytes." (PMID 38274944, 2023). "Similarly, in RECs, hyperglycemia determines SIRT1 down regulation followed by a decrease of mitochondrial antioxidant enzymes levels through pathways controlled by p300 and Fork head box protein O1 (FOXO1)." (PMID 35409409, 2022). "Overactivated FoxO1 can also promote the expression of inducible NO synthase in DCM, and further induce the nitrosylation of target proteins such as glyceraldehyde-3-phosphate dehydrogenase and caspase-3, leading to post-hyperglycemia myocardial cell death and myocardial dysfunction." (PMID 36147338, 2022). "Furthermore, the increase in PlGF release in response to hyperglycaemia was lost in HUVEC following knock-down of FOXO1, and no IGF-1-mediated suppression of PlGF production was observed in the presence of constitutively active FOXO1." (PMID 34381074, 2021). "Interestingly, the mRNA levels of FoxO1 target genes in skeletal muscle were strongly upregulated, reflecting insulin signaling insufficiency, after DT and STZ+S961, the two conditions that led to hyperglycemia." (PMID 27092792, 2016). "Consequently, we found out that ROS-induced cellular injury, apoptosis, and autophagy under hyperglycemia were further exacerbated by silencing FoxO1 or FoxO3a, and that P-PostC could not confer cardiac protection in the absence of FoxO1 or FoxO3a." (PMID 34753510, 2021). "In conclusion, HM-chromanone ameliorates hyperglycemia by PI3K/AKT and improves the FOXO1 in ob/ob mice." (PMID 37432173, 2023). "Likewise, IRS-2−/− mice failed to exhibit insulin-mediated phosphorylation of forkhead box protein O1 (FOXO1), a key regulatory protein of hepatic glucose production, which led to increased gluconeogenesis and hyperglycemia." (PMID 31319588, 2019).